CHCHD4P4 (coiled-coil-helix-coiled-coil-helix domain containing 4 pseudogene 4)
Gene: Processed pseudogene on chromosome 3 (11,234,256 to 11,234,582, reverse strand). Ensembl gene ENSG00000213964.
Diseases named in the same sentence as CHCHD4P4 in open-access papers:
CHCHD4P4 is named in the same sentence as 2 diseases in open-access papers, as found by Europe PMC text mining. Sharing a sentence is not in itself a finding about the gene and the disease. The quoted sentences say what the papers report.
kidney disease (1 paper, 2021). "More importantly, CHCHD4P4 overexpression inhibited cell proliferation by promoting the apoptosis of HK-2 cells treated with COM, suggesting that CHCHD4P4 might aid the early diagnosis and treatment of kidney disease." (PMID 34386039, 2021).
CHCHD4P4 also shares sentences with these, for which no sentence is quoted: renal fibrosis (1 paper).